NGF (nerve growth factor)
Diseases named in the same sentence as NGF in open-access papers (continued):
Sharing a sentence is not in itself a finding about the gene and the disease.
cancer (326 papers, 2006 to 2026). A tumor composed of atypical neoplastic, often pleomorphic cells that invade other tissues. "The NGF signaling axis was associated with the sensitivity of cancer cells to EGFR inhibitors in malignant tumor." (PMID 40612670, 2025). "NGF secretion is induced by excessive reactive oxygen species (ROS) production by cancer cells, which is associated with excessive pain generation." (PMID 39099944, 2024). "The NGF/TrkA axis is closely associated with the progression of many cancers and poor clinical outcomes." (PMID 38816365, 2024). "The nerve growth factors (NGF) referred to as neurotrophins have been associated with cancer-induced bone pain; however, the role of NGF in osteosarcoma has yet to be elucidated." (PMID 39247831, 2024). "NGF is implicated in inflammatory, neuropathic, surgical, and cancer pain, highlighting the need to study contributions of NRP1 across pain pathologies." (PMID 39589827, 2024). "Sensory nerve fibers undergoing pathological sprouting in cancers has been reported, which was driven by NTFs, especially the nerve growth factor (NGF), released from tumors and their associated stromal cells." (PMID 36900158, 2023). "Among them, the nerve growth factor (NGF) that is released by both epithelial PC cells and carcinoma-associated fibroblasts (CAFs) triggers the activation of various intracellular signaling cascades, thereby promoting the acquisition of a metastatic phenotype." (PMID 36941697, 2023). "NGF and its receptors (TrkA and p75NTR) are implicated in cancer growth, CSC proliferation, and immune system evasion." (PMID 35681602, 2022). "Our results showed that targeting NGF and autophagy inhibited proliferation and invasion by inhibiting autophagic initiation and autophagic flux and caused apoptosis of SCs, cancer cells and DRGs in vitro." (PMID 35109895, 2022). "Several lines of evidence underline that the binding of NGF to TrkA receptor mediates proliferation, differentiation and survival of both neurons and cancer cells via the activation of PI3K/Akt, Ras/MAPK and PLCγ pathways." (PMID 36354700, 2022). "Emerging evidence has revealed that the NGF signaling pathway involves inflammatory hyperalgesia and cancer-associated pain." (PMID 33392191, 2020). "Most of these genes were found to be involved in cancer progression-associated pathways such as gene expression, cell cycle regulation and nerve growth factor signaling." (PMID 30809433, 2019). "Particularly, Nerve Growth Factor (NGF) and its specific receptor Tropomyosin related kinase A (TrkA) have been implicated in initiation and progression of many aggressive cancers." (PMID 31812953, 2019). "Consistent with this, short-term exposure of cancer-associated fibroblasts, mesenchymal stem cells, and osteoblasts to pH 6.8 promotes the expression of inflammatory and nociceptive mediators (NGF, BDNF, IL6, IL8, IL1b and CCL5)." (PMID 28903357, 2017). "NGF also induces an increase of calreticulin levels, a chaperone that has been associated with survival and migration of cancer cells." (PMID 28245631, 2017). "In this context, NGF/TrkA/p75NTR gained enormous attention as potential targets for treatments against cancer-associated pain, leading to the development and trial of several classes of small-molecule-inhibitors and antibodies targeting this signaling axis." (PMID 27536251, 2016). "Targeting signaling pathways associated with PNI, such as NGF/tyrosine receptor kinase A (TrkA), may effectively alleviate cancer pain and improve treatment outcomes for tumors." (PMID 40421086, 2025). "Furthermore, NE promotes the β2‐AR‐dependent secretion of nerve growth factor (NGF) by cancer‐associated fibroblasts (CAFs), thereby increasing intratumoral sympathetic innervation and NE accumulation." (PMID 41415714, 2025). "While nerve growth factor (NGF) is implicated in cancer progression, its role in OS angiogenesis remains unclear." (PMID 39860039, 2025).
cancer (continued). "NGF and TrkA have been implicated in pain associated with inflammation, nerve injury, and cancer." (PMID 39589827, 2024). "Indeed, the activation of the NGF/TrkA signaling pathway is responsible for pain, and therefore, either NGF or TrkA is a potential therapeutic target for alleviating cancer-associated pain." (PMID 39766161, 2024). "The most common signalling pathway associated with cancer pain is the NGF pathway." (PMID 39723256, 2024). "Moreover, both pain initiation and the maintenance of cancer pain were associated with an enlarged expression of nerve growth factor (NGF) and brain-derived neurotrophic factor (BDNF), and the increased release of tryptase and ATP." (PMID 38730655, 2024). "The possible causes of higher NPY expression include increased peptide production in cancer cells under the influence of external factors, e.g. nerve growth factor (NGF) from the nerves, or internal factors caused by transcriptional upregulation, as well as changes in methylation of the coding gene." (PMID 36583743, 2023). "NGF is overexpressed in most human breast and pancreatic cancers, and its overexpression is associated with enhanced proliferation, invasion, and tumorigenicity of cancer cells." (PMID 37047688, 2023). "In addition to causing bronchial asthma, NGF and its receptors have been found to be over-expressed in malignant tumors in the ovaries, breasts, lungs, pancreas, skin, liver, stomach and thyroid." (PMID 38049878, 2023). "NGF and its receptor TrkA have been implicated in the development of many aggressive cancers." (PMID 36072337, 2022). "This neurotrophic effect of NGF in cancer may be associated with a large number of human malignancies as well as other neurotrophins and may have an effect on cancer pain." (PMID 36406133, 2022). "In addition, the activation of NGF-TrkA pathway is also implicated in the transmission of pain signals as well as in tumorigenesis and metastasis formation in different types of cancer." (PMID 36139382, 2022). "NGF is associated with cancer cell progression and survival in several different types of cancers." (PMID 34815382, 2021). "NGF is associated with progression and survival in several cancer types." (PMID 34283074, 2021). "Concomitantly, in vitro and in vivo cancer models showed that NGF is involved in cancer cell progression, invasion and chemoresistance, underlying that the NGF axis may represent a new therapeutic target in these tumors." (PMID 34209730, 2021). "It is believed that this positive regulation induced by NGF is closely associated with post-transcriptional modifications that regulate expression of the channels and play an essential role in the maintenance of pain associated with cancer." (PMID 35053150, 2021). "It contributes to understanding the molecular impact of specific Cav-1 mutations in certain cancers where TrkA, p75NTR, and NGF are involved in the tumorigenic response, while raising the question of the potential impact on trafficking of other receptors and channels." (PMID 28338624, 2017). "The role of NGF in inflammation and tumorigenesis as a component of the inflammatory system, its interaction with the various components of the respective microenvironments, its ability to cause epigenetic changes, and its role in the treatment of cancer have been highlighted in this paper." (PMID 38392180, 2024). "In addition, these two receptors of NGF are implicated in cancer development." (PMID 33428936, 2021). "Therefore, inhibiting NGF could play a dual effect against both cancer growth and cancer-associated pain." (PMID 33392191, 2020). "Besides, the TRKA signaling pathway due to NGF stimulation has been linked to cancer before." (PMID 25296882, 2014). "Targeting the NGF–TrkA axis can diminish cancer cell migration along neurites in vitro and inhibit PNI in vivo." (PMID 41556039, 2026).
cancer (continued). "Cancer cells promote nerve growth and guide cancer cell migration along neural tracts by secreting nerve growth factors (NGF), neurotrophic factors, and chemokines." (PMID 40861469, 2025). "Existing studies suggest that NGF and B-NGF jointly participate in angiogenesis, promoting cancer progression." (PMID 40292253, 2025). "For instance, NGF can stimulate signaling pathways in cancer cells, so exacerbating their malignancy." (PMID 40092993, 2025). "After intrathecal injection of anti-nerve growth factor, a significant anti-injury effect was seen with increased μ opioid receptor expression compared to the cancer pain group." (PMID 40860871, 2025). "For example, in cholangiocarcinoma, activation of the NGF/TrkA pathway promotes the proliferation and invasion of cancer cells." (PMID 40421086, 2025). "Functional validation revealed that anti-NGF treatment reduced neurite outgrowth, linking NGF signaling to cancer-driven innervation." (PMID 40243726, 2025). "Cancer cells can release neurotrophic substances, including NGF and Artemin, to stimulate the development of nerve fibers toward tumor tissues." (PMID 40092993, 2025). "Upon doxorubicin chemotherapy, the reactive upregulation of NGF exacerbates drug resistance and cancer pain, highlighting the importance and urgency of targeting NGF." (PMID 40783715, 2025). "It has also been shown that anti-NGF therapy is efficacious in preventing pain-inducing adaptations in the functional brain network after sustained injurious inputs of cancer-induced osteodynia." (PMID 40860871, 2025). "The Schwann cells reciprocate with cancer cells and increase adenosine production with enhanced secretion of IL-6, TNFα and NGF, which ultimately have an augmenting effect on cancer proliferation, migration and invasion." (PMID 40002847, 2025). "In response to this invasion, neurons increase neurite outgrowth, creating a reciprocal relationship that intensifies the cancer's growth and spread, driven in part by neurotrophic factors like nerve growth factor (NGF)." (PMID 39842382, 2025). "Regarding the role of NGF in the development and maintenance of cancer pain, as well as the analgesic effects of anti-NGF therapy, two articles are worth mentioning." (PMID 41301953, 2025). "NGF and its receptor play key roles in skeletal system, neurological diseases, cancer and angiogenesis, but its targeted therapy still faces many challenges." (PMID 40860871, 2025). "Monoclonal antibody targeting NGF, used in clinical trials for cancer-related bone pain, shows some analgesic effect." (PMID 40860871, 2025). "This heparanase expression is upregulated in astrocytes by nerve growth factor (NGF) in response to factors secreted by cancer cells, including TGF-β1, IL-1β, and bFGF." (PMID 41268299, 2025). "In fact, cancer cells produce growth factors, namely NGF, which stimulate nerve sprouting, especially via the stimulation of new adrenergic nerve fibres and through the switch of sensory fibres into adrenergic ones." (PMID 39940997, 2025). "In vitro studies have demonstrated that NGF can inhibit the proliferation ofneurogenic cancer cell lines and induce their differentiation." (PMID 40771851, 2025). "In the glucose-deprived environment, oral mucosal cancer tissue secreted nerve growth factor (NGF) via activation of c-Jun triggered by reactive oxygen species (ROS)." (PMID 40456735, 2025). "The c-Jun promoter has consensus AP1 sites, and c-Jun can regulate its own expression levels in cancer cell lines, NGF-deprived sympathetic neurons and kainic acid treated hippocampus." (PMID 40067879, 2025). "The inhibition of the nerve growth factor (NGF)–neurotrophic tyrosine kinase receptor (NTRK1) pathway has been shown to inhibit cancer proliferation, reduce innervation and increase the overall survival of mice when treated together with gemcitabine." (PMID 40075699, 2025).
cancer (continued). "Emerging evidence suggests that NGF plays a significant role in triggering the EMT in specific cancer cell types, further enhancing their invasive potential and metastatic capabilities." (PMID 38392180, 2024). "There seems to be a potential relationship between cancer and psychosocial biology via neurotransmitters and neurotrophins such as the NGF." (PMID 38791953, 2024). "NGF signaling pathways have been shown to induce changes in cell morphology and enhance the migratory and invasive properties of these cancer cells, contributing to the aggressive behavior of tumors." (PMID 38392180, 2024). "Cancer cells secrete various growth factors (NGF and hepatocyte growth factor [HGF]), chemokines and metabolites in an autocrine and/or paracrine manner." (PMID 39119085, 2024). "The context-dependent actions of NGF in cancer underscore the complexity of the signaling networks in which it operates and its interaction with diverse cellular components within the TME." (PMID 38392180, 2024). "NGF plays a central role in the intricate signaling network within Cancer Stem Cell (CSC) metabolism." (PMID 38392180, 2024). "Many have suggested effective approaches to inhibit cancer via NGF inhibition, suggesting a promising therapeutic potential." (PMID 38392180, 2024). "Further research and clinical studies are warranted to establish the effectiveness of anti-NGF therapy specifically in the realm of cancer treatment." (PMID 38542008, 2024). "As this review illustrates, there is still little known about this interaction between the NGF and cancer." (PMID 38791953, 2024). "The influential role of NGF signaling and its contribution to cancer-related features have led to an interest in anti-NGF treatment for its management." (PMID 39906323, 2024). "Understanding the factors that drive this pro-apoptotic activity will be crucial for the development of novel therapeutic approaches that harness NGF-induced cell death pathways to combat cancer progression." (PMID 38392180, 2024). "TrkB and TrkC also interact with neurotrophins like NGF and aberrant expression has been reported in different cancers." (PMID 38392180, 2024). "NGF and TrkA are crucial for the growth and survival of neurons and cancer cells, contributing to pain through neural sensitization." (PMID 39064636, 2024). "Because of its activity in both cancer and nerves, the NGF was first called nerve growth-promoting activity." (PMID 38791953, 2024). "Evidence from published studies indicates that within the TME of HNCs, NGF is predominantly secreted by cancer cells." (PMID 39906323, 2024). "Recent studies have shown that cancer cells express neurotrophic markers such as NGF, BDNF, and GDNF and release axon guidance molecules such as Ephrin B1 to promote axonogenesis, neurogenesis, and neuronal reprogramming." (PMID 38920662, 2024). "Research indicates that NGF, along with B-NGF, is involved in angiogenesis and can facilitate cancer progression 134-137." (PMID 39132165, 2024). "The reciprocal interactions between cancer cells and the surrounding stromal and immune cells mediated by NGF highlight its potential as a promising target for cancer therapeutics." (PMID 38392180, 2024). "Nerves that stimulate the release of ACh through cholinergic stimulation can enhance the expression of NGF in the gastric epithelium, leading to the advancement of cancer." (PMID 37566075, 2023). "In this review, we have highlighted the role of (pro)NGF/TrkA inhibitors in cancer therapeutic strategies." (PMID 37046604, 2023). "Beyond their impact in PC biology, the drivers of NGF-dependent signaling are currently targeted to improve the patient’s survival and the cancer-related pain." (PMID 36941697, 2023). "For example, one of the most promising pathways to date for targeting cancer nerve growth is the NGF signaling pathway, a neurotrophic factor, known to have a neurodevelopmental role." (PMID 37719704, 2023).
cancer (continued). "Cancer cells produce diffusible cancer growth factors (CGFs) such as nerve growth factor, epidermal growth factor or platelet-derived growth factor that promote the growth of the conspecifics and suppress the normal cells (alien to the cancer cells)." (PMID 38111808, 2023). "In this review, the therapeutic potential of NGF/TrkA inhibitors (anti-NGF and Trk TKIs) in cancers as curative and palliative drugs will be presented." (PMID 37046604, 2023). "Intriguing findings on NGF signaling derangement have been discovered in the gender-related cancers, including PC." (PMID 36941697, 2023). "As before discussed in this review, many evidence correlates the NGF signaling with the androgenic axis in the brain, but also in some cancer types, including prostate and colon." (PMID 36941697, 2023). "After many years of investigation, we now appreciate that aberrations and/or derangement of NGF signaling are involved in the pathogenesis of various human diseases, including cancers." (PMID 36941697, 2023). "Cancer cells release chemical messengers such as axon guidance molecules, NGF and vascular endothelial growth factor (VEGF) that by autocrine or paracrine loop modulate the activity of nerves when they are in the immediate microenvironment." (PMID 36941697, 2023). "Commonly, NGF is an upstream regulator of the mTOR pathway and few studies have shown that mTOR can regulate the expression of NGF in cancer cells." (PMID 35449152, 2022). "In non-cancer skeletal pain models, anti-NGF therapy has shown promising results, e.g., in mice with femoral fracture, anti-NGF therapy reduces pain behaviours without affecting bone healing." (PMID 36688083, 2022). "Work in models of cancer bone pain has demonstrated NGF-dependent ectopic sprouting of nerve fibers contributes to bone pain." (PMID 35262711, 2022). "It seems that NGF exerts both stimulatory and inhibitory effects on human cancers with overall effects determined by the ratio of TrkA to p75NGFR." (PMID 35155573, 2022). "NGF-TrkA signaling system is thought to be involved in the progression of various cancers and was suggested to play a role in perineural growth and invasion in HNSCC." (PMID 35571032, 2022). "These various actions of NGF are dependent on cell type and the presence of NGF receptors in the cancer cells." (PMID 35681586, 2022). "A nervous growth factor that deserves particular mention is NGF because of its widespread activity in cancer biology." (PMID 36499024, 2022). "An enhanced expression of the NGF and TrkA in pancreatic cancer was considered to be related to the perineural invasion of cancer cells." (PMID 35571032, 2022). "The potential molecular mechanism by which autophagy of SCs promotes PNI in PanCa is that neurotrophic factors, such as NGF, secreted by cancer cells can induce autophagy of SCs by upregulating ATG7 expression." (PMID 35109895, 2022). "GNC-siRNA complex at 100 nM concentration showed 75% downregulation of NGF mRNA expression compared to 17% reduction of NGF mRNA expression by free siRNA, resulting in cancer growth and migration of PANC-1 cells." (PMID 35652096, 2022). "This interaction seems to be predominantly orchestrated by the chemoattractive action of cancer-releasing nerve growth factor (NGF) upon SC p75NTR." (PMID 35455973, 2022). "NGF is also synthesized, stored and released by vascular endothelial cells, platelets, fibroblasts and cancer cells." (PMID 36354700, 2022). "We also found that the expression of cleaved PARP1 and cleaved caspase-3 increased in the RO + CQ group, indicating that the combination of the NGF inhibitor RO and the autophagy blocker chloroquine can induce the apoptosis of cancer cells." (PMID 35109895, 2022). "In our previous studies, we demonstrated that NGF induces the association between TrkA and CD44 in cancer cells." (PMID 35346305, 2022).